TTF1 (transcription termination factor 1)
Diseases named in the same sentence as TTF1 in open-access papers (continued):
Sharing a sentence is not in itself a finding about the gene and the disease.
thyroid (continued). "It is easy to diagnose and differentiate from other spindle cell lesions of thyroid by histological morphology, immunohistochemical staining with CT, CgA, Syn, CD56, and TTF-1." (PMID 34838061, 2021). "The absence of any nuclear labelling against TTF1, together with a negative assessment against thyroglobulin, disregards a thyroid origin of the neoplasm." (PMID 41180242, 2025). "TTF-1 can be useful in confirming the diagnosis of a thyroid primary lacking a well-differentiated growth pattern (papillary or follicular) or unusual cytology, such as poorly differentiated thyroid carcinoma, mucoepidermoid carcinoma, and secondary tumors." (PMID 37324272, 2023). "Thyroid-like low-grade nasopharyngeal papillary adenocarcinoma (TL-LGNPPA) is a rare neoplasm characterized by morphological analogy to papillary thyroid carcinoma and the abnormal expression of thyroid transcription factor-1 (TTF-1)." (PMID 32872013, 2020). "Meanwhile, in the thyroid lesions, the malignant cells showed negative staining for TG and TTF-1, which confirmed that lesions were not thyroid in origin." (PMID 23833651, 2013). "In contrast, negative immunoreactivity to TTF-1 and Tg, in addition to negative clinical thyroid investigations and the absence of metastatic disease elsewhere, confidently excludes the possibility of a metastatic thyroid follicular carcinoma in our case." (PMID 23533895, 2013). "However, the observed association between TTF-1 expression and the incidence of ICI-induced thyroiditis has not yet been definitively attributed to antigenic cross-reactivity." (PMID 40535343, 2025). "However, the tumor was unequivocally negative for thyroid-associated markers such as TTF1, PAX8 and thyroglobulin, setting it apart from other thyroid-related salivary gland tumors that are not uncommonly positive for one or several of these proteins." (PMID 32519264, 2021). "Moreover, in our patient, tumor cells in the pleural effusion were positive for TTF-1 but negative for thyroglobulin on immunohistochemistry, which made it even more difficult to identify the origin of the malignant pleural effusion as being the thyroid." (PMID 25532447, 2014).
thyroid tumor (40 papers, 2005 to 2025). A benign or malignant neoplasm affecting the thyroid gland. "In this respect, the possibility that the high levels of ALCAM expression in thyroid tumors may indicate a reprogramming in transcriptional activity due the loss TTF-1 may deserve further investigation." (PMID 21364949, 2011). "It is reported that TTF-1 and TG are demonstrable through immunohistochemical methods in approximately 75% of thyroid tumors." (PMID 40575170, 2025). "Namely, the detection of immunopositive staining for thyroglobulin and the thyroid transcription factor-1 (TTF-1) can indicate primary thyroid neoplasms." (PMID 39050581, 2024). "The applications of calcitonin, CEA, and TTF1 in head and neck tumors have primarily focused on thyroid tumors." (PMID 39259067, 2024). "Primary thyroid tumors of follicular origin stain positive for thyroglobulin (TG) and thyroid transcription factor-1 (TTF-1)." (PMID 37990226, 2023). "MHC-I molecules are involved in the initiation and pathological process of thyroid autoimmune diseases and thyroid tumors, while TTF-1 is the main factor regulating MHC-I molecules." (PMID 34631891, 2021). "As the TTF-1 expression decreases with tumor differentiation from benign thyroid tumor, follicular thyroid carcinoma, and undifferentiated carcinoma, TTF-1 can be used as a prognostic indicator for judging the malignancy of thyroid tumors." (PMID 34631891, 2021). "TTF-1 is thought to be expressed specifically in most thyroid tumors and in a significant subset of pulmonary neoplasms." (PMID 30631609, 2018). "Because of similarity between the neuroendocrine tumor and a thyroid tumor-specifically, follicular-like characteristics-immunohistochemical stains for thyroglobulin, TTF1, and calcitonin were performed." (PMID 28316853, 2017). "The thyroid tumors are usually reactive for immunohistochemical markers of thyroglobulin and thyroid transcription factor-1 (TTF-1)." (PMID 25685581, 2015). "Melan-A, inhibin, and some other markers have been found to be positive in patients with ACC, and thyroglobulin and TTF-1 have been found to be positive in patients with thyroid neoplasms in immunohistochemical studies." (PMID 23889916, 2013). "TTF-1 seems able to induce differentiation and decrease proliferation of tumor cells in thyroid tumors." (PMID 22940844, 2012). "Despite the fact that TTF-1 is known as a specific marker for lung and thyroid tumours, this case shows that primary non small-cell breast carcinomas can also be positive." (PMID 20565809, 2010). "In ARO cells, a greater efflux rate had been also observed after overexpression of exogenous NIS gene inserted in a viral vector; similarly, only a faint iodide uptake reappeared in BHP18-21v thyroid tumour cells expressing TTF1." (PMID 16029487, 2005). "However, when their expression is above the threshold level (especially the abnormal expression of TTF-1), they can induce the occurrence of thyroid tumors." (PMID 34631891, 2021). "Histologically, the left thyroid lobe biopsy of our patient presents negative markers for primary thyroid neoplasms (TTF-1 and TG) and positive markers for hepatitis-associated disease (AFP and GPC3), confirming the presence of poorly differentiated metastatic HCC." (PMID 40575170, 2025). "For example, thyroid transcription factor-1 (TTF-1) is widely known as a marker for pulmonary adenocarcinoma but is also highly expressed in thyroid tumors and may uncommonly also be expressed in carcinomas originating from other primary sites, including, for example, colorectal carcinoma." (PMID 22263108, 2012). "Markers such as Tg, TTF-1, and PAX8 typically indicate primary thyroid tumors since SITs lack these markers." (PMID 39980562, 2025). "In contrast, PAX8, TTF1, and CDX2, markers for renal carcinomas, pulmonary and thyroid neoplasms, and small intestine or the appendix, respectively, were constantly negative in all RenNETs of our series and in the cases of the literature." (PMID 37405461, 2023).
thyroid tumor (continued). "We then tested for markers TTF-1 and CK7, which allowed us to determine the lung as the primary source and differentiate it from thyroid neoplasms." (PMID 35706725, 2022). "The differential diagnosis between parathyroid and thyroid tumours, paraganglioma, haematological or metastatic tumours can be clarified via PTH, chromogranin A, TTF-1, calcitonin, LCA, CD56 and vimentin, among others." (PMID 35805976, 2022). "p16 positive cells were confirmed to be thyroid tumor cells through a morphological assessment and the expression of BRAFV600E (assessed by the BRAFV600E-specific monoclonal antibody) and TTF-1 (the thyroid specific transcription factor-1)." (PMID 31906302, 2020). "Negative staining for TTF1 and calcitonin (not shown) excluded a differentiated (follicular or medullary) thyroid neoplasm." (PMID 40762649, 2025). "TTF-1 is expressed in pulmonary adenocarcinomas, but not in metastatic lung tumors (except thyroid tumor metastases), so this marker is useful to distinguish between primary and metastatic lesions." (PMID 20796281, 2010). "Regarding immunohistochemistry, most ITTC cases were positive for CD5, a marker for carcinoma of thymic origin, as well as for p63, CD117, CK5/6 and negative for thyroid transcription factor 1 (TTF-1), to distinguish it from other thyroid tumors, also described in the literature." (PMID 41278290, 2025). "Negativity for TTF1 and thyroglobulin ruled out thyroid neoplasm." (PMID 28003924, 2016). "In this regard, immunohistochemistry for thyroglobulin (which may, however, be negative in anaplastic thyroid carcinoma) and TTF-1 (more specific) is very useful in distinguishing primary (positive) from secondary (negative) thyroid tumors." (PMID 25628901, 2015). "Furthermore, immunoperoxidase stains for thyroglobulin and TTF-1 were negative, excluding the possibility of a thyroid neoplasm." (PMID 15943858, 2005). "Differential diagnosis with secondary thyroid tumors depends on non-reactivity to immunohistochemical (IHC) markers for TFCC (thyroglobulin - TG and TTF1)." (PMID 31063281, 2019). "Although the immunophenotype of our case indicated epithelioid–squamoid differentiation, the characteristic expression patterns of TTF-1, Pax-8, and CD5 were absent in the thyroid tumor." (PMID 29885658, 2018). "TTF-1 mRNA is detected in papillary carcinomas (PTC) but not in anaplastic carcinomas; therefore TTF-1 is considered as a marker to distinguish between these two types of thyroid neoplasms." (PMID 21814573, 2011).
breast carcinoma (38 papers, 2007 to 2026). "This is in contrast with previously published literature in which PTRF has been shown to interact with pS2/TTF1 which on its turn needs ER as key transcriptional factor in order to be expressed and is associated with a better clinical outcome in breast cancer." (PMID 26892682, 2016). "In fact, in a case like ours, additional immunohistochemical markers were performed (such as, GATA‐3, calretinin, TTF‐1) for the diagnosis of breast cancer." (PMID 41239938, 2026). "If primary ER + breast cancers are excluded, TTF1/napsin A were instead the key tissue markers in male CK7 + /CK20 − and in female CK + /CK20 − ER − MUO biopsies." (PMID 36346458, 2023). "Reviewing previous literature indicates that TTF-1 positive breast cancer has been demonstrated with both clones." (PMID 23675755, 2013). "Follow-up time after tumor diagnosis for TTF-1 positive cases varied from 29-61 months, and one patient (#1) died from breast cancer." (PMID 23675755, 2013). "We recently documented a case of breast cancer with positive expression of TTF-1, and we subsequently wanted to establish the frequency of TTF-1 expression in a population-based setting of breast cancer." (PMID 23675755, 2013). "Here, we analyzed expression of TTF-1 protein (clone SPT24) by immunohistochemical staining of sections from paraffin embedded tumor samples in 247 primary breast cancers from the population-based Norwegian Breast Cancer Screening Program." (PMID 23675755, 2013). "The presence of a positive TTF-1 reaction in the in situ component as well as in the invasive component in this case gives strong support for primary breast carcinoma." (PMID 20565809, 2010). "SOD1 has been associated with tumor formation, TTF1 is also thought to be a negative prognostic factor in breast cancer, and FN14 has been associated with metastasis." (PMID 41149583, 2025). "When a primary breast cancer is suspected, TTF1 and GATA3 are the most relevant markers." (PMID 29881714, 2018). "Expression of TTF1 was also demonstrated in basal phenotype breast cancers." (PMID 24581278, 2014). "Regarding primary breast cancer, some cases with TTF-1 positivity have been reported." (PMID 23675755, 2013). "In conclusion, our population-based study indicates that TTF-1 expression may be present in 3% of primary breast cancers." (PMID 23675755, 2013). "For example, TTF-1 and CDX2 can also show positive rates of 4.6% and 1.8% in breast cancer respectively." (PMID 40822238, 2025). "Malignant melanoma expressed HMB45, MelanA, and S-100; small cell lung cancer expressed TTF-1, CD56, and CgA; hepatocellular carcinoma expressed GPC-3, hepatocyte, and Sall4; breast cancer expressed ER, PR, Her-2, and GCDFP-15." (PMID 37608278, 2023). "CLDN6 expression in breast cancer is regulated by transcription factors such as HIF-1a, FoxA2, Gata6, and TTF-1 at the claudin 6 promoter." (PMID 37762277, 2023). "The pathology of the thyroid samples disclosed a secondary malignancy of poorly differentiated breast cancer with immunophenotypes CK7+, CK 20-, GATA3+, TTF-1-, P40-, S100-, CDX-2-, Thyroglobulin-, Pax8-, and P63-." (PMID 37048792, 2023). "We performed TTF-1 and CKAE1-AE3 immunostaining on six CAM tumor slides obtained from lung and breast cancers, selected according to the immunochemical profile of the original tumor." (PMID 36077622, 2022). "We next examined the expression of three estrogen-responsive genes in these two cell lines; namely Growth Regulation By Estrogen In Breast Cancer 1 (GREB1), Cyclin D1 (CCND1) and Trefoil Factor 1 (TTF1)." (PMID 30370249, 2018). "Metastatic breast carcinoma cells typically exhibit positive expression of mammary epithelial differentiation markers (e.g., GATA, Mammaglobin, ER/PR, TRPS1) and negative expression of thyroid follicular cell markers (e.g., Thyroglobulin, TTF-1, PAX-8)." (PMID 41199830, 2025).
breast carcinoma (continued). "In our patient, immunohistochemical negativity for neuroendocrine, breast cancer markers, and TTF‐1, together with the absence of clinical evidence of recurrence, supported the diagnosis of primary pulmonary BSCC." (PMID 40515571, 2025). "In our case, chromogranin A, synaptophysin, CD56, and TTF1 were not stained initially, and the diagnosis was triple negative primary bilateral breast cancer." (PMID 39292386, 2024). "Focal expression of TTF1 has been described in breast carcinoma, while 20% of primary pulmonary adenocarcinomas do not express TTF1." (PMID 29881714, 2018). "TTF-1 is expressed in about 75% of pulmonary adenocarcinomas, and no breast carcinomas have been reported to be positive for TTF-1 except rare small cell carcinomas of the breast." (PMID 25274100, 2014). "Metastatic thyroid carcinoma (papillary, follicular, or medullary) can resemble papillary or apocrine breast lesions; however, TTF-1 (SPT24 clone) and PAX8 positivity support thyroid origin, while breast carcinomas are typically negative." (PMID 41510417, 2025). "Neuroendocrine markers (synaptophysin and chromogranin A), breast cancer markers (ER, PgR, GCDFP‐15, GATA3) and thyroid transcription factor‐1 (TTF‐1) were negative." (PMID 40515571, 2025). "Immunohistochemical staining of thyroid, which exhibited positive GATA3 and HER2, and negative TTF1, TG, GCDFP15, PR and ER, confirmed breast carcinoma metastases to the thyroid." (PMID 33776925, 2021). "The CK7-positive, TTF-1-negative, CK20-negative, Hoechst-positive signature observed in our ER-negative patient is consistent with breast cancer." (PMID 26695546, 2016). "Breast cancer cells typically stain positive for CK7, ER and are negative for CA125, CK20, and TTF1." (PMID 18036260, 2007).
non-small cell lung carcinoma (36 papers, 2009 to 2025). A group of at least three distinct histological types of lung cancer, including non-small cell squamous cell carcinoma, adenocarcinoma, and large cell carcinoma. "Interestingly, epFoxm1−/− tumors maintained normal expression levels of TTF-1, a lung epithelial-specific transcription factor, implicated in controlling cellular proliferation during embryogenesis and formation of non-small cell lung cancer." (PMID 19672312, 2009). "Interestingly, the epFoxm1−/− tumors still maintained normal expression levels of the TTF-1 protein, a lung epithelial-specific transcription factor, implicated in controlling cellular proliferation during embryogenesis and formation of non-small cell lung cancer." (PMID 19672312, 2009). "A core needle biopsy of the LUL mass indicated a poorly differentiated malignant neoplasm suggestive of non-small cell lung cancer (NSCLC) with focal TTF-1 positivity." (PMID 41293380, 2025). "Thyroid transcription factor-1 (TTF-1) has been widely studied in non-small cell lung cancer, which is considered as an independent prognostic factor in patiens with non-small cell lung cancer." (PMID 32702788, 2020). "Still, morphology and TTF-1 and p40 is sufficient for diagnosis in the majority of non-small cell lung cancer cases." (PMID 30718697, 2019). "Double-immunohistochemistry were performed in 105 tumor samples paring with normal lung tissue from non-small cell lung cancer patients by using monoclonal antibody of P63/NapsinA and TTF-1/CK7." (PMID 30037373, 2018). "A recent meta-analysis showing that TTF-1 overexpression is related to a favorable prognosis for non-small cell lung carcinoma patients, appears to strengthen the results being reported here." (PMID 30127783, 2018). "TTF-1 mRNA expression was evaluated in 10 non-small cell lung cancer (NSCLC) cell lines by quantitative real-time RT-PCR (qRT-PCR)." (PMID 22940844, 2012). "This Cas-CHDC-powered electrochemical RNA-sensing technology chip successfully detects six non-small-cell lung carcinoma-related RNAs (miRNA-17, miRNA-155, TTF-1 mRNA, miRNA-19b, miRNA-210, and EGFR mRNA), with results consistent with those obtained from qRT-PCR." (PMID 39194596, 2024). "Moreover, some specific immunohistochemistry markers which were not known to be expressed in ALCL but in the other malignancies can support the diagnosis, including rhabdomyosarcoma markers MyoD1 and Myogenine and non-small cell lung cancers marker TTF-1." (PMID 27612448, 2016). "TS-1 treatment for the carcinoma with an unknown primary site may be useful in patients who are not candidates for systemic platinum-based chemotherapy, because TTF1+ carcinoma patients are treated like non-small cell lung cancer patients." (PMID 24370171, 2013). "Additionally study of TTF-1 related molecular pathways might provide new insights regarding cancer initiation, progression, and treatment for this relatively large group of non-small cell lung cancer patients." (PMID 25594059, 2014). "Using non-small cell lung cancer (NSCLC) as a model, the assay successfully detected exosomal miR-21 and TTF-1 mRNA with high sensitivity, requiring as little as 1 μL of serum." (PMID 40723868, 2025). "Characterization of the assay included screening a panel of multiple human cancer tissues and an independent cohort of non-small cell lung carcinoma (NSCLC, n = 118) characterized by TTF-1, p63, CK5/6, and CK7 IHC." (PMID 24244672, 2013). "Due to the small size of the specimen, immunohistochemical markers were performed and revealed positive staining for cytokeratin 7 and negative for TTF-1, napsin A and p 40, which were consistent with non-small cell lung carcinoma." (PMID 33832072, 2021). "Non-small cell carcinoma displaying positive CK 7 and negative to TTF-1, napsin-A, and p 40 immunostaining was diagnosed." (PMID 33832072, 2021).